MCL1 (MCL1 apoptosis regulator, BCL2 family member)
Diseases named in the same sentence as MCL1 in open-access papers (continued):
Sharing a sentence is not in itself a finding about the gene and the disease.
tumor (continued). "Using murine tumour models, the data provided here demonstrate the suitability of MCL-1 as a rational drug target for the treatment of pulmonary adenocarcinoma." (PMID 32913197, 2020). "The MEK1/2 inhibitor binimetinib potentiated the activity of venetoclax and ABT-737 under conditions that mimic the CLL tumor microenvironment via downregulation of MCL-1 activity, BIM and BCL-xL expression." (PMID 33139702, 2020). "Enhances radiation-induced apoptosis by inhibiting STAT3; it also downregulates Mcl-1, cyclin D1 and survivin expression, overcomes resistance to radiation in cells and suppresses tumor growth in vivo." (PMID 32872659, 2020). "Although promising results were obtained in a subset of MM patients treated with venetoclax, this activity is restricted to tumor clones with high BCL-2:MCL-1 and BCL-2:BCL-xL expression ratios as well as reduced electron transport chain activity." (PMID 33308268, 2020). "This correlates with high-level expression of BCL-XL and MCL-1 in cell lines and a large cohort of patient tumour samples." (PMID 33298868, 2020). "The combination of ABT-263 with the specific MCL-1 inhibitor VU661013 was able to induce tumor cell death in vivo and a synergistic reduction in tumor growth." (PMID 33308268, 2020). "While suppression of Mcl-1 alone did not yield in significant apoptosis induction, combined inhibition of Bcl-xL/Bcl-2 and Mcl-1 led to strong cell killing and a reduction of tumor growth in patient-derived xenograft models in vivo." (PMID 32752193, 2020). "Knock down of MCL-1 or BCL-XL enhanced tumor cell death whereas over-expression of BCL-XL was protective as was knock down of BAX, BAK and BAD." (PMID 32047722, 2020). "Both venetoclax and S63845 exerted selective cytotoxicity against the tumor cells which highly expressed Bcl-2 or Mcl-1 protein, but had limited efficacy in tumor cells with low expression of Bcl-2 or Mcl-1 consistent with previous studies." (PMID 33362794, 2020). "Immunohistochemistry and qRT-PCR showed BIM levels (protein and mRNA) increased in tumours from mice receiving Cisplatin, and unexpectedly, MCL-1 levels were reduced in tumours following A-1331852 treatment." (PMID 33298868, 2020). "This compound showed selective inhibition of MCL-1, and its oral administration to tumor-bearing mice resulted in tumor regression." (PMID 33308268, 2020). "This study provides the first evidence showing that the anti-apoptotic MCL-1 protein stability is regulated by the deubiquitinase USP7 in tumor cells (arsenic and BaP co-exposure-transformed cells)." (PMID 32802178, 2020). "First, we analysed MCL-1 genomic gains during tumour evolution, taking further advantage of the TRACERx study." (PMID 32913197, 2020). "For instance, treatment of tumours with the multi-tyrosine kinase inhibitor sunitinib enhances the stability of Mcl-1 and induces activation of the mTORC pathway, which leads to sunitinib resistance." (PMID 33064779, 2020). "Subsequently, we compared the molecular features of c-Myc/MCL1/Cre and c-Myc/MCL1/pCMV mouse tumor lesions." (PMID 33187130, 2020). "Meanwhile, MCL-1 expression was significantly decreased in the tumors of shrimp miR-965-treated mice, showing that the targeting of MCL-1 by shrimp miR-965 led to the inhibition of the tumor-initiating ability and tumor development of MSLC in vivo." (PMID 32586376, 2020). "Another MCL-1 specific inhibitor AZD-5991 shows significant anti-tumor activity in vivo with complete regression in mouse models of MM and AML, based on which a phase I clinical trial has been set up for patients with hematological malignancies (NCT03218683)." (PMID 32335811, 2020). "Taken together, our results manifested that shrimp miR-965 suppressed the tumor-initiating ability and tumor development of MSLC in vivo by decreasing MCL-1." (PMID 32586376, 2020). "Reducing the expression of MCL1 can inhibit the proliferation of tumor cells and lead to cell cycle arrest." (PMID 32675387, 2020).
tumor (continued). "The tumor volume and tumor weight in the deguelin-treated Mcl-1 5KR mutant group were significantly larger than that of the deguelin-treated Mcl-1 WT group." (PMID 32081857, 2020). "The protein levels of Bcl-2 and Mcl-1 in various types of tumor tissues were found to be frequently augmented at a higher ratio than the other anti-apoptotic proteins in the Bcl-2 family." (PMID 32260280, 2020). "We provide evidence that the selective pressure for the evasion of apoptosis during tumour evolution results in recurrent genomic gains of MCL-1 with high frequency in NSCLC patients." (PMID 32913197, 2020). "Functionally, “osmotic reprogramming” of the tumor environment grants contextual synthetic lethality to BCL-XL inhibitors in dually BCL-XL/MCL-1-protected cells." (PMID 32312973, 2020). "Both BH3 mimetics exerted dose-dependent cytotoxic activity, which strongly connected to Bcl-2 and Mcl-1 expression in these tumor cells showing high expression of Bcl-2 or Mcl-1 on both RNA and protein levels." (PMID 33362794, 2020). "It acts as miRNA sponge by inhibiting the functions of tumour suppressor miR-363-3p, which in turn leads to Mcl1 expression, a target of miR-363-3p and allows Mcl1 mediated oncogenic role in ATC." (PMID 33126409, 2020). "Studies have shown that important tumor-related factors, such as the epidermal growth factor receptor, sarbox-2, c-myc, and McL-1, are regulated by USPs." (PMID 32164618, 2020). "Inhibition of EGFR by TKI, erlotinib, disrupts the interaction between Bim and Mcl-1 and sensitizes tumor cells to ABT-737 treatment." (PMID 32276600, 2020). "Mitochondria Bcl‐2 family proteins play a major role in tumor cell survival, and antiapoptotic proteins, such as Bcl‐2 or Mcl‐1, are often highly expressed in tumor cells." (PMID 34766113, 2020). "Over-expression of anti-apoptotic proteins (e.g., Bcl-2, Mcl-1 or Bcl-xL) is observed in many human malignancies including NSCLC, and associated with tumor progression, poor prognosis and chemotherapy resistance." (PMID 32212793, 2020). "Studies have shown that increased levels of Mcl-1 in tumor cells is correlated with high levels of cell survival and development of resistance to diverse chemotherapeutic agents including ABT-737." (PMID 32212793, 2020). "Degradation of Mcl-1 by β-TrCP mediates glycogen synthase kinase 3-induced tumor suppression and chemosensitization." (PMID 32081857, 2020). "Recent studies revealed that the decrease of Mcl-1 plays a crucial role in TKI or other targets therapy-mediated tumor suppression." (PMID 32276600, 2020). "Nonetheless, after a long latency, also c-Myc/MCL1/Cre developed neoplastic lesions and reached an elevated tumor burden by 36 weeks post injection." (PMID 33187130, 2020). "We validated this strategy in vivo using a RMS patient-derived xenograft model and observed a reduction in tumor growth with a tendency to stabilization with the sequential combination of vincristine and the MCL-1 inhibitor S63845." (PMID 32801295, 2020). "Mcl-1 is an member of the anti-apoptotic Bcl-2 family proteins that is expressed in various tissues and tumor cells." (PMID 32212793, 2020). "Modern approaches such as BH3 profiling and large-scale CRISPR screens were able to shed light on the prominent role of MCL-1 in tumor cell death evasion." (PMID 33308268, 2020). "This dependency on MCL-1 is further driven by both genetic and functional alterations in tumor cells that will be addressed in the current review and presented alongside upcoming treatment strategies that specifically target MCL-1 dependency in tumor cells." (PMID 33308268, 2020). "Further tumor tissue analysis showed that the positive staining of the proliferation marker Ki-67 is significantly less in the tumors from injection of MCL-1 knockdown cells, compared to the tumors from injection of shRNA control cells." (PMID 32802178, 2020).
tumor (continued). "To date, rare studies have reported the relationship between the MCL1 copy number and the tumor immunogenic microenvironment." (PMID 32527042, 2020). "Genetic deletion of Mcl-1 was confirmed by RNA in situ hybridisation and genomic DNA analysis of primary cultures from tumour lesions." (PMID 32913197, 2020). "MiR-199a-3p has been demonstrated to attenuate some oncogenes and antiapoptotic genes (i.e., MET, mTOR, MCL-1 and Bcl-XL, Stat3), suggesting its potential tumor suppressive role." (PMID 32565738, 2020). "The reduction of Mcl-1 protein by GSK3β- β-TrCP axis-mediated Mcl-1 ubiquitination and degradation enhances tumor-killing efficacy of chemotherapy agents." (PMID 32276600, 2020). "The highly selective CDK9 inhibitor, AZD4573, induced apoptosis and subsequent cell death in hematologic cancer models in vitro and favored tumor regression in tumor xenografts in vivo, through the indirect inhibition of Mcl-1." (PMID 32455818, 2020). "Conversely, knockdown or therapeutic targeting of USP9X destabilizes MCL-1 and sensitizes tumor cells to BCL-2/BCL-xL inhibitors." (PMID 33308268, 2020). "Chromosomal gain mediated amplification of Mcl-1 and Bcl-xL were found to be the most frequent alterations across 26 tumor types, particularly in solid tumors." (PMID 32335811, 2020). "Several tumor types show heterogeneous dependence on MCL-1 including breast, lung, multiple myeloma (MM) and MYC-driven lymphomas." (PMID 32335811, 2020). "Mcl-1 and Bcl-xL, anti-apoptotic members of the Bcl-2 family, are frequently upregulated in various tumor types." (PMID 32612994, 2020). "We show that genomic gains of the pro-survival MCL-1 gene occur with high frequency during tumour evolution in pulmonary adenocarcinoma." (PMID 32913197, 2020). "In this regard, preliminary data from our group seem to exclude the relevance of the cholesterol pathway or fatty acid uptake mechanisms in the survival of tumor lesions from c-Myc/MCL1/Cre mice." (PMID 33187130, 2020). "The rapid degradation of MCL1 results in an increase in the sensitivity of these tumor cells to chemotherapy." (PMID 32354135, 2020). "We argue that as an addiction, tumours favour the presence of MCL-1 and, when present, they become highly dependent on it." (PMID 32913197, 2020). "Mcl-1 and Bcl-xL are frequently increased in various tumor types and promote tumor progression as pro-survival molecules." (PMID 32612994, 2020). "Consistent with our in vitro results, we observed reduced levels of TCL-1, pAKT, MCL-1, and Cyclin A in tumor tissue from AUY922-treated mice compared with that from un-treated mice." (PMID 31992715, 2020). "MCL1 overexpression has been reported in HCC, where it associates with low tumor differentiation grade and poor patients’ prognosis." (PMID 33187130, 2020). "WapMyc tumor cells express high levels of Bcl-2, Bcl-XL and Mcl-1, and are sensitive to ABT-737 ex vivo." (PMID 30728358, 2019). "The tumor suppressor effect of miR-29b-3p was partly reversed by H19 overexpression after co-transfection, and the mRNA level and protein level of MCL-1 were positively correlated with H19." (PMID 30728351, 2019). "SF3b-targeting splicing modulators have also been employed in disruption of hard-to-drug oncogenes, e.g., MCL1, through mis-splicing as an alternative approach to targeting these oncogenes required for tumor survival." (PMID 30635584, 2019). "The treatment resulted in the reduction of known CDK9 targets, i.e. Bcl‐2 and Mcl‐1 in tumour tissues." (PMID 31398271, 2019). "Meanwhile, the recognized target genes of miR-101, such as c-Fos, ZEB1 and Mcl-1, known to promote tumor growth, were significantly decreased in AML cells transduced with sh-SNHG1." (PMID 31615767, 2019). "MCL-1 was highly expressed in the tumor core from the oral cavity compared to the normal tissue, whereas this was not evident in the advancing front." (PMID 31801952, 2019).
tumor (continued). "As a key element of the initiation translation complex, eIF4E participates in the translation of tumor–associated proteins, such as c‐MYC, cyclin D1, and MCL‐1 (Kosciuczuk, Saleiro, & Platanias, 2017)." (PMID 30891950, 2019). "MCL1 is known to play an important role in regulating the sensitivity of tumor cells to BCL2 inhibitors as MCL1 overexpression is associated with resistance to ABT199." (PMID 31752970, 2019). "We furthermore show that TYK2 is activated by an autocrine loop involving IL-10 and IL-22 and that STAT1 and STAT3 are essential mediators of aberrant tumor cell survival through activation of the pro-survival protein MCL1." (PMID 30131584, 2019). "Dual inhibition of BCL-XL and MCL-1 resulted in a significant dose-dependent reduction in tumor size compared to controls." (PMID 31801952, 2019). "CycT also decreases the levels of two regulators promoting OXPHOS, MYC and MCL1, and effectively alleviates tumor hypoxia." (PMID 30723259, 2019). "The development of more efficacious anti-MCL-1 drugs will require both the synthesis of new more active inhibitors and the definition of biological assays able to better define the anti-tumor activity of these inhibitors and to predict their clinical efficacy." (PMID 30813354, 2019). "Many apoptosis regulators, including survivin and Mcl-1, modulate the anticancer effects of sorafenib and regorafenib in tumor cells." (PMID 31349793, 2019). "In contrast, endogenous amplification/high expression of MCL1 or BCL2A1, which confers “oncogene addiction” in tumor cells, is associated with hypersensitivity to E7107-induced cell death." (PMID 30635584, 2019). "For the common gene MCL1, studies have found that the gene is closely related to human tumor formation." (PMID 31319533, 2019). "We observed downregulation of Mcl-1 in the brains of tumor-bearing animals after treatment with 55 mg/kg CYC065 over a 9-day period (compared with a 14-day treatment window with 500 mg/kg seliciclib)." (PMID 31842413, 2019). "TVA caused a significant increase in Mcl-1 expression in 5-8F and CNE-2 cells, which indicates that tumor cells are resistant to TVA." (PMID 30738430, 2019). "MCL‐1 protein is a special protein in the process of controlling apoptosis, and MCL‐1 can protect tumour cells against apoptosis." (PMID 31497917, 2019). "Inhibition of tumor growth was accompanied by a reduction in anti-apoptotic Bcl-2, Bcl-XL, Mcl-1, survivin, and VEGF in tumor tissue, and decreased expression of proliferation mediators cyclin D and c-Myc." (PMID 31671769, 2019). "This led to the decreased expression of pro-survival protein MCL-1, a synergistic inhibition of cell survival, and the reduction of tumor growth in this PDX model of TNBC." (PMID 31101835, 2019). "Among the antiapoptotic members, Mcl-1 and Bcl-2 are antiapoptotic members of the Bcl-2 family and are key survival factors in various neoplasms." (PMID 30678274, 2019). "Co-expression of MCL1 and Cre in B1P and B1P-Myc mice resulted in a significant decrease in tumor latency compared to mice in which only Cre was delivered (180 vs. 238 days and 70 vs. 126 days, respectively)." (PMID 30674894, 2019). "Consistent with in vitro assay, WP1130 treatment also lead to the decreased of USP24 and Mcl-1 levels in Jurkat tumor xenografts." (PMID 30911287, 2019). "We have also provided evidence in this study to suggest that CYC065 is able to cross the BBB in mice-phosphor-Rb, Cyclin E and Mcl-1 downregulation within the tumor tissue of CYC065-treated animals." (PMID 31842413, 2019). "Anti-apoptotic proteins like BCL-2, BCL-XL, and MCL-1 are well-known for maintaining tumor cell survival and are therefore attractive drug targets." (PMID 30406027, 2018). "High levels of MCL1 expression in PEL tumor cells further support its oncogenic role and viability as a drug target in PEL." (PMID 30111820, 2018). "Previous studies have revealed critical roles of BCL-xL and MCL-1 in tumor cell response to BCL-2/BCL-xL/BCL-w inhibition." (PMID 30250075, 2018).
tumor (continued). "Tumour growth was monitored following injection and knockdown of MCL-1 was shown to substantially impair tumour growth." (PMID 29339815, 2018). "The expression of MCL1 in paraffin tumor samples was analyzed by immunohistochemistry as described in Materials and Methods section." (PMID 29568373, 2018). "The results indicate that, while MCL-1 is a key factor, mitochondrial priming potential can also be affected by additional proteins inside the tumor cells." (PMID 30250075, 2018). "Tumor lysates showed the Mcl-1 overexpression group exhibited decreased cleavage of PARP in response to H89/tetrandrine treatment." (PMID 29866132, 2018). "Taken together, our results indicated that pharmacological inhibition of USP13 by spautin-1 reduced MCL1 protein abundance and increased tumor cell sensitivity to ABT-263." (PMID 29335437, 2018). "Tumours were allowed to establish and when they reached ~ 5 mm diameter, treatment with the MCL-1-specific inhibitor UMI-77 (60 mg/kg) or vehicle control commenced by intraperitoneal injection 5 times per week." (PMID 29339815, 2018). "NF-κB target gene encoding proteins such as MMP-9, VEGF, MCL-1, XIAP, C-FLIP, and Cyclin-D1, promote metastasis, angiogenesis, antiapoptosis, and proliferation in HCC leading to tumor progression." (PMID 29535278, 2018). "PEITC also inhibited the tumor growth by inhibiting MCL-1 in our GBM 8401 ectopic xenografts in vivo." (PMID 30201893, 2018). "At this point, it would be interesting to analyze in human biopsies BCL-2, MCL-1 or BCL-xL levels during follow-up to test their correlation with the tumor response under sorafenib." (PMID 29682179, 2018). "Seliciclib is an inhibitor of Cdk 2, 7 and 9, which has been shown to induce tumor shrinkage as well as induce tumor apoptosis, reduced expression of Mcl-1, cyclin D1 and pRB in paired tumor biopsies obtained following around 8 days of treatment." (PMID 29789630, 2018). "In conclusion, we identified USP13 as a novel deubiquitinase to stabilize MCL1 and modulate tumor cell sensitivity to BH3 mimetic inhibitors." (PMID 29335437, 2018). "Western blots on the tumor samples confirmed that the combination treatment markedly decreased Mcl‐1, c‐Myc, Bcl‐2, and Bcl‐xL." (PMID 29761903, 2018). "Of 4 tumours treated with trastuzumab plus chemotherapy, an increase in MCL-1 and decrease in BAX was observed in 1 case." (PMID 30305055, 2018). "Encouragingly, tumour cells seem particularly sensitive to MCL-1 inhibition suggesting an adequate therapeutic window." (PMID 29339815, 2018). "To understand the link between c-MET signaling and Mcl-1 regulation, we focused on tumor cell metabolism." (PMID 29743557, 2018). "Of the 4 lapatinib-treated tumours, 2 showed an increase in MCL-1 and a decrease in BAX mRNA levels post-treatment, similar to the changes observed in the SKBR3-L cells." (PMID 30305055, 2018). "Mcl-1 expression is higher in human HCC tissue than in the adjacent non-tumor liver, and it also protects HCC cells against the drug-induced apoptosis of chemotherapeutic drugs." (PMID 29348495, 2018). "Altered splicing of the mRNAs coding for the anti-apoptotic proteins BCL-X and MCL-1 can also contribute to the anti-tumour activity of targeting the spliceosome." (PMID 29796170, 2018). "We further report that genetic or pharmacological inhibition of USP13 considerably reduces MCL1 protein abundance and significantly increases tumor cell sensitivity to BH3 mimetic inhibitors targeting BCL-2 and BCL-XL." (PMID 29335437, 2018). "Repression of MCL1 exerts cytotoxic effects in tumor cells, indicating that MCL1 is a promising target for the treatment of a wide range of tumors." (PMID 30139386, 2018). "In summary, these results elucidate that magnolin promotes autophagy and cell cycle arrest through LIF/Stat3/Mcl-1 pathway, which in turn prevents the tumor growth of CRC." (PMID 29899555, 2018).